NLRP3 (NLR family pyrin domain containing 3)
Diseases named in the same sentence as NLRP3 in open-access papers (continued):
Sharing a sentence is not in itself a finding about the gene and the disease.
gas gangrene (2 papers, 2019 to 2025). A severe condition resulting from bacteria invading healthy muscle from adjacent traumatized muscle or soft tissue. "The expression of genes for α-toxin, an activator of NLRP3 inflammasome, and ethanolamine ammonia-lyase, a factor responsible for the progression of gas gangrene, was significantly upregulated during 2'-FL assimilation compared to growth on lactose." (PMID 40102238, 2025). "Taken together, our data suggest that proinflammatory responses triggered by NLRP3-mediated inflammasome are involved in the progression of myonecrosis induced by PFO." (PMID 31708887, 2019). "NLRP3-mediated necrosis or induction of IL-1β appears to be involved in the myonecrosis induced by PFO." (PMID 31708887, 2019). "Since myonecrosis induced by infection with the α-toxin mutant (Δplc) was inhibited in the NLRP3-deficient mice, PFO-driven myonecrosis was shown to be NLRP3-dependent." (PMID 31708887, 2019). "Our data showed that the pore-forming action of PFO triggers inflammasome activation via NLRP3, which is necessary for the induction of myonecrosis by PFO." (PMID 31708887, 2019). "We further demonstrated that PFO-mediated myonecrosis is dependent on NLRP3." (PMID 31708887, 2019). "Furthermore, we demonstrated, for the first time, that the myonecrosis induced by PFO was dependent on NLRP3." (PMID 31708887, 2019). "The area of myonecrosis after infection was significantly decreased in the case of Δplc infection, but not in the case of infection with WT C. perfringens or the Δpfo mutant, suggesting that the limited action of PFO in inducing myonecrosis is clearly dependent on NLRP3." (PMID 31708887, 2019). "Although the myonecrosis was found to be largely dependent on the α-toxin, PFO also induced myonecrosis to a lesser extent, again through the mediation of NLRP3." (PMID 31708887, 2019). "Furthermore, we first demonstrated that the myonecrosis induced by PFO was dependent on NLRP3, suggesting that the PFO produced by C. perfringens induces myonecrosis in infected muscle tissues via NLRP3-mediated inflammasome activation." (PMID 31708887, 2019).
genital warts (2 papers, 2016 to 2021). "In particular, imiquimod, a prescription medication used to treat genital warts, stimulates mtROS generation by inhibiting the quinone oxidoreductases NQO2 and mitochondrial Complex I, which triggers the NLRP3 inflammasome activation." (PMID 33414419, 2021). "Imiquimod, which is used for superficial SCC and BCC and genital warts, is a ligand for both TLR7 and NLRP3, therefore inducing both IL-1 and interferon." (PMID 27768771, 2016).
H1N1 virus infection (2 papers, 2018 to 2021). "CS exposure and H1N1 virus infection can activate NF-κB signaling pathway and NLRP3 inflammasome and promote proinflammatory cytokine (IL-6, IL-1β) release and Th17 cell differentiation." (PMID 34393799, 2021). "Our previous study demonstrated that the swine influenza virus (SIV) infection induced NLRP3 inflammasome activation leading to the IL-1β production in primary porcine alveolar macrophages (PAMs)." (PMID 30096906, 2018). "We previously showed that the swine influenza virus (SIV) infection induced NLRP3 inflammasome-mediated IL-1β production in primary porcine alveolar macrophages (PAMs), and we were interested in examining the upstream signaling events that are involved in this process." (PMID 30096906, 2018).
HELLP syndrome (2 papers, 2020 to 2022). A life-threatening condition that can potentially complicate pregnancy. "In addition, NLRP3 plays a pivotal role in the development of HELLP syndrome (hemolysis, elevated liver enzymes, and low platelet count), a serious complication that may result in maternal death." (PMID 35632746, 2022).
hemophagocytic lymphohistiocytosis (2 papers, 2022 to 2025). "XIAP plays roles in cell survival, activation, and negative regulation of the NLRP3 inflammasome, in a manner that patients with XIAP loss-of-function variants are at risk for virally triggered hemophagocytic lymphohistiocytosis." (PMID 36510129, 2022). "Targeting NLRP3 with BET inhibitors limits disease in the cytokine storm syndrome, secondary hemophagocytic lymphohistiocytosis." (PMID 40632844, 2025).
hemorrhagic cystitis (2 papers, 2016 to 2021). Inflammation of the bladder resulting in bloody urine. "We found that elevated NLRP3 expression and ensuing activation of caspase 1 (cleaved caspase 1) to be associated with the model of hemorrhagic cystitis." (PMID 27995963, 2016). "In summary, we found that LUT can inhibit oxidative stress, inflammation, and apoptosis through TXNIP/NLRP3 and NF-κB, which then produces protection against CYP-induced hemorrhagic cystitis and effectively improves bladder voiding dysfunction." (PMID 34804174, 2021). "Therefore, TXNIP/NLRP3 and NF-κB may be potentially effective targets for hemorrhagic cystitis." (PMID 34804174, 2021). "Therefore, this study aims to verify the therapeutic effect of LUT on acute hemorrhagic cystitis in rats and to further determine whether the NF-κB signal pathway and the TXNIP/NLRP3 axis are the therapeutic targets of LUT against bladder injury." (PMID 34804174, 2021).
Hepatitis B (2 papers, 2020 to 2024). "It has been reported that NLRP3 inflammasome was activated in peripheral blood mononuclear cells (PBMCs) from patients infected with acute hepatitis B by quantitative real-time PCR (qRT-PCR) and enzyme-linked immunosorbent assay (ELISA)." (PMID 38817443, 2024). "Here, we summarize the current knowledge about their roles in hepatitis B and C. NLRP3 inflammasome can be activated and regulated by HBV and HCV." (PMID 38817443, 2024). "The regulation and the role of NLRP3 inflammasome in Hepatitis B need to be further studied under physiological conditions." (PMID 38817443, 2024). "Besides NLRP3 inflammasome, IFI16 and AIM2 inflammasomes participate in the pathological process of hepatitis B, and NALP3 inflammasome may sense HCV infection in hepatocytes." (PMID 38817443, 2024).
hereditary periodic fever syndrome (2 papers, 2008 to 2013). An instance of periodic fever syndrome that is caused by an inherited modification of the individual's genome. "NLRP3, NOD2, MEFV, and PSTPIP1 are the genes responsible for 4 of the syndromes collectively termed hereditary periodic fever syndromes (HPFS)." (PMID 18576390, 2008).
hypercoagulability (2 papers, 2022 to 2025). "Total AV+ MVs, mainly reflecting hypercoagulability, correlated positively to NLRP3 gene expression (r = 0.545, p = 0.009)." (PMID 36140297, 2022).
hyperphosphatemia (2 papers, 2021 to 2026). Abnormally high level of phosphate in the blood. "Other CKD-related factors, such as vitamin D3 deficiency and hyperphosphatemia, may also disturb the functions of the inflammasome, as vitamin D3 is crucial for NLRP3-dependent IL-1β secretion and hyperphosphatemia polarizes macrophages into the M2-like phenotype." (PMID 33430226, 2021).
hypoxic-ischemic encephalopathy (2 papers, 2020 to 2021). "However, it has been found in a newborn animal study of hypoxic-ischemic encephalopathy, that NLRP3 deficiency increases brain injury." (PMID 33123073, 2020). "NLRP3 inflammasome activation and pyroptosis have been described in neonatal hypoxic-ischemic encephalopathy." (PMID 34691200, 2021).
idiopathic dilated cardiomyopathy (2 papers, 2014 to 2024). Decreased function of the heart associated with cardiac enlargement and congestive heart failure, of unknown cause. "Higher signaling through NLRP3 has been recently related to adverse outcome in other forms of cardiac dysfunction as idiopathic dilated cardiomyopathy." (PMID 25412247, 2014).
idiopathic inflammatory myopathies (2 papers, 2024 to 2025). "A potential role for NLRP3 inflammasome dysregulation in disease pathogenesis has been suggested in idiopathic inflammatory myopathies and other skeletal muscle disorders, including inherited myopathies." (PMID 40080076, 2025). "NLRP3 inflammasome is also involved in the pathogenesis of idiopathic inflammatory myopathy through multiple mechanisms." (PMID 39723212, 2024). "Due to the rare nature of the disease, research on idiopathic inflammatory myopathies(IIMs) is relatively limited, mainly converged on NLRP3 and AIM2." (PMID 39723212, 2024). "Recent research has revealed the significance of NLRP3 inflammasome signaling cascade in idiopathic inflammatory myopathies." (PMID 39723212, 2024).
idiopathic scoliosis (2 papers, 2017 to 2022). A scoliosis with no known cause. "To examine the roles of the cGAS-STING axis and NLRP3 inflammasome in IVD degenerative progression, we collected tissue samples from patients who underwent open spine surgery or lumbar discectomy surgery because of idiopathic scoliosis or lumbar disc herniation." (PMID 35145201, 2022).
Impaired glucose tolerance (2 papers, 2016 to 2017). An abnormal resistance to glucose, i.e., a reduction in the ability to maintain glucose levels in the blood stream within normal limits following oral or intravenous administration of glucose. "Studies in mice have linked impaired glucose tolerance and cognitive decline to enhanced expression of NLRP3 inflammasome pathway during aging." (PMID 28798751, 2017). "The increased TNF-α levels in aged mice were reported to enhance the expression of NLRP3 inflammasome in adipose tissue and liver, which results in impaired glucose tolerance." (PMID 28798751, 2017).
insulinoma (2 papers, 2024). "CATB participates in ATG7-induced nod-like receptor 3 (NLRP3)-inflammasome activation in a rat insulinoma cell line." (PMID 38542221, 2024). "In a rat insulinoma cell line, ZEA promoted activation of NLRP3 inflammasomes by modulating NF-κB/p65 signaling to induce NLRP3-dependent pyroptosis and inflammation." (PMID 39057975, 2024).
itch (2 papers, 2023 to 2024). "Given that Nlrp3-knockout (KO) mice exhibited increased scratching behavior in a DNFB-induced chronic itch model, we further investigated whether IL-18 or IL-1β plays a vital role in NLRP3 inflammasome activation." (PMID 39867900, 2024).
Klebsiella Infections (2 papers, 2019 to 2025). Infections with bacteria of the genus KLEBSIELLA. "In vitro experiments confirmed the contribution of NLRP3 to caspase-1 activation and IL1β release following Klebsiella infection." (PMID 30452654, 2019).
latent infection (2 papers, 2023 to 2024). "We outline nicotine’s role in the establishment of active and latent infection in the brain and posit the NLRP3 inflammasome as a common pathway by which HIV-1 and nicotine promote neuroinflammation in PWH." (PMID 39529883, 2024). "Thus, the regulation of the NLRP3 inflammasome may represent a major target in controlling latent infection and frequent inflammation by the HSV-1 virus." (PMID 38001788, 2023).
lipodystrophy (2 papers, 2022 to 2023). A congenital or acquired disorder characterized by abnormal loss or redistribution of the adipose tissue in the body. "Clinical observation provided novel findings of lipodystrophy in a PRAAS patient, and a knock-in mouse model revealed the contribution of NLRP3-mutant hematopoietic cells to cartilage overgrowth." (PMID 35603217, 2022).
lung aspergillosis (2 papers, 2014 to 2019). "In addition, the intraperitoneal injection of IL-37 significantly decreases the expression of NLRP3 in the mouse lung aspergillosis model." (PMID 31736917, 2019).
malignant glioma (2 papers, 2019 to 2021). A grade III or grade IV glioma arising from the central nervous system. "NLRP3 and NF-κB p65 were observed to have elevated expressions in malignant glioma tissues." (PMID 34239588, 2021).
malignant mesothelioma (2 papers, 2022 to 2024). A malignant neoplasm of the pleura or peritoneum, arising from mesothelial cells. "Two chemotherapeutics (doxorubicin and cisplatin) can activate the NLRP3‒GSDMD pyroptosis axis to exert antitumour effects in malignant mesothelioma." (PMID 38804602, 2024).
meningoencephalitis (2 papers, 2020 to 2021). Inflammation of the meninges and brain, generally secondary to an infectious cause. "In addition, E. coli can cause meningoencephalitis by increasing the inflammatory response and activating the TLR2/TLR4/MyD88 and the NLRP3 inflammasome pathways." (PMID 35145923, 2021).
metastasis (2 papers, 2023 to 2026). The spread or migration of cancer cells from one part of the body (where they first appeared) to another. "Lower CASP1 expression was significantly associated with smaller tumor size (p = 0.005), whereas lower NLRP3 expression was associated with axillary lymph node metastasis (p = 0.003)." (PMID 41865075, 2026).
microcephaly (2 papers, 2019 to 2021). A congenital or acquired developmental disorder in which the circumference of the head is smaller than normal for the person's age and sex. "However, because ofthe presentation of microcephaly in the patients with intactAKT3 gene, the other candidate genes such as NLRP3,HNRNPU, SMYD3, and KIF26B have been suggestedto cause microcephaly." (PMID 31210441, 2019). "Presence of NLRP1, NLRP3, and AIM2 together with elevated IL-1β, IL-18, and IL-33 could be detected in the brain of ZIKV-infected patients with microcephaly." (PMID 33796483, 2021).
muscle disorders (2 papers, 2021 to 2025). "In this review, we summarize and present the current knowledge regarding the function of NLRP3 in diseased skeletal muscle, and discuss the potential therapeutic options targeting the NLRP3 inflammasome in muscle disorders." (PMID 34831246, 2021).
muscular atrophy (2 papers, 2018 to 2022). "In addition, the inhibitors of NLRP3 signaling did not exert detrimental effects on body weight, at variance with DEX, which, being a systemically acting glucocorticoid derivative, is known to be associated with a variety of adverse effects, including muscular atrophy." (PMID 30559669, 2018).
Mycoplasma pneumonia (2 papers, 2022). "NOD2 and TLR5 SNPs were associated with pleuritis, whereas NLRP3 SNPs were associated with an index of mycoplasmal pneumonia." (PMID 36428390, 2022). "One in vitro study of MGD on serum of children with Mycoplasma pneumonia also showed that MGD suppressed L-1β, IL-18, TNF-α, down-regulated NLRP3, pro-IL-1β, Caspase-1, pro-Caspase-1, and GSDMD-N in infected cultures and mitigated NLRP3 overexpression-induced pyroptosis." (PMID 36120338, 2022).
Myelodysplasia (2 papers, 2018 to 2023). Clonal hematopoietic stem cell disorders characterized by dysplasia (ineffective production) in one or more hematopoietic cell lineages, leading to anemia and cytopenia. "If as in rodents, methylene blue also inhibits NLRP3 inflammasome function in human myelodysplasia a trial of adjunctive methylene blue treatment in transfusion dependent, low risk myelodysplasia where marrow inflammation and apoptosis predominates, would be worth trying." (PMID 30101125, 2018).
optic atrophy (2 papers, 2021 to 2023). A disorder characterized by loss of optic nerve fibers. "The incidences of papilledema and optic atrophy in the Chinese adult NLRP3-AID patients of moderate type were similar to those in the Caucasian NLRP3-AID patients of severe type." (PMID 34099780, 2021).
Osteolysis (2 papers, 2022 to 2023). Osteolysis refers to the destruction of bone through bone resorption with removal or loss of calcium. "On the contrary, NLRP3 silencing attenuates the promotive effect of conditioned exosomes on M1 polarization in a particles-induced osteolysis model." (PMID 36969165, 2023). "Given that NLRP3 inflammasome activation by wear particles is a key step in the course of osteolysis, a wear particle-induced osteolysis mouse model was used for in vivo studies." (PMID 35996168, 2022). "A recent study has found that macrophages can activate the NLRP3 inflammasome and initiate subsequent pyroptosis to affect AL pathogenesis in mice model of cobalt-chromium-molybdenum (CoCrMo) alloy particles-induced osteolysis." (PMID 36969165, 2023).
Osteopenia (2 papers, 2016 to 2017). Osteopenia is a term to define bone density that is not normal but also not as low as osteoporosis. "Since IL-1β has been shown to mediate the effects of estrogen deficiency on bone, we hypothesized that the NLRP3 inflammasome, via maturation of IL-1β plays a role in estrogen-dependent osteopenia." (PMID 28747793, 2017).
pancreatic adenocarcinoma (2 papers, 2021 to 2023). "NLRP3 gene expression was found elevated in the pancreas of patients with pancreatic adenocarcinoma (n = 179) when compared with normal tissue (n = 171)." (PMID 37772994, 2023). "Inhibition of the NLRP3 inflammasome through an NLRP3-specific antagonist could also reduce the cell viability in pancreatic adenocarcinoma." (PMID 34393801, 2021). "Furthermore, NLRP3 signaling has shown to participate in tumor progression in a mouse model of PDAC and to correlate with reduced survival in patients with pancreatic adenocarcinoma." (PMID 37772994, 2023).
pelvic inflammatory disease (2 papers, 2020 to 2022). Pelvic inflammatory disease (PID) is an acute or chronic inflammation in the pelvic cavity. "In the present study, we found that SSD exerted a protective effect on pelvic inflammatory disease through activation of the SIRT1 signaling and elimination of the NLRP3 inflammasome." (PMID 36106027, 2022).
pneumonitis (2 papers, 2024 to 2025). An inflammatory process affecting the lung parenchyma. "Mounting evidence highlights the pivotal role of NLRP3 inflammasome activation in the pathogenesis of both LPS-induced pneumonitis and RP." (PMID 41209552, 2025). "Consistent with this, inhibition of the NF-κB/NLRP3 pathway has been shown to have significant therapeutic effects in murine models of CMV-pneumonitis." (PMID 38675960, 2024). "NLRP3 activation dynamics differ between the two pneumonitis models." (PMID 41209552, 2025). "As radiation exposure and LPS stimulation activate inflammasomes (including NLRP3 and AIM2)—key molecular complexes that trigger pyroptosis—this process directly contributes to disease development in both pneumonitis types 56-60." (PMID 41209552, 2025).
premature ovarian failure (2 papers, 2022 to 2023). "Furthermore, the characteristics of premature ovarian failure were more significant in Nrf2 knockout mice than in wild-type mice, especially the expression of NLRP3 and TXNIP." (PMID 35153783, 2022). "Our results suggested that daphnetin is likely to be a candidate drug for premature ovarian failure treatment and it is mostly possible referred to the molecular mechanism of increasing Nrf2 expression and inhibiting NLRP3 activation in the ovarian aging process." (PMID 35153783, 2022).
progeria (2 papers, 2021 to 2024). "To evaluate the role of the NLRP3 inflammasome in progeria, we examined the expression of the components of the NLRP3 inflammasome pathway in HGPS and control fibroblasts." (PMID 34448355, 2021). "Therefore, this HGPS treatment strategy, focused on the inhibition of NLRP3 inflammasome complex, could constitute an alternative therapy to slow down disease progression in patients with progeria." (PMID 34448355, 2021). "Targeting NLRP3 may be a novel potential therapeutic strategy for progeria treatment." (PMID 34448355, 2021).
radiculopathy (2 papers, 2020 to 2025). Disease involving a spinal nerve root (see spinal nerve roots) which may result from compression related to intervertebral disk displacement; spinal cord injuries; spinal diseases; and other conditions. "We provided evidence in our current study that NLRP3 inflammasome activation and cell pyroptosis were associated with radiculopathy in a rat model of NCLDH." (PMID 32982664, 2020).